UBB (ubiquitin B)
Diseases named in the same sentence as UBB in open-access papers (continued):
Sharing a sentence is not in itself a finding about the gene and the disease.
neurodegenerative disease (8 papers, 2014 to 2023). A disorder of the central nervous system characterized by gradual and progressive loss of neural tissue and neurologic function. "Therefore, the presence of UBB+1 can be a useful indicator in other neurodegenerative diseases as shown recently for ER-associated degradation (ERAD) dysfunction in familial encephalopathy with neuroserpin inclusion bodies (FENIB)." (PMID 25852488, 2015). "However, reducing Drp1 stability by abnormal and continuous UBB+1 expression could ultimately cause pathological problems, such as the synaptic loss of neurons in neurodegenerative diseases." (PMID 24941066, 2014). "UBB+1 accumulates in several neurodegenerative diseases other than G-PDC, including tauopathies (e.g., AD) and polyglutamine (polyQ) diseases (e.g., Huntington’s disease) and has been shown to be detrimental to neurons." (PMID 29615966, 2018). "The role of the UPP in glia with regard to neurodegenerative disease has been somewhat neglected, and it would be interesting to find out how UBB+1 impacts neuroglia." (PMID 29615966, 2018). "Intracellular accumulation of ubiquitin-B+1 (UBB+1), a frameshift mutant of ubiquitin-B, is indicative of a dysfunctional UPS and has been implicated in several disorders, including neurodegenerative disease." (PMID 27966098, 2017). "However, the role of UBB in neurodegenerative disease is well studied, and therefore, we performed studies to check alterations in the gene expression and protein level of UBA52 during the onset of PD." (PMID 36497031, 2022). "Ubiquitin-B+1 (UBB+1) is a frameshift mutant of ubiquitin-B (UBB) that has been found to accumulate in a variety of disorders, including neurodegenerative diseases." (PMID 27966098, 2017). "However, it is intriguing that ubiquitin A-52 (UBA-52) and polyubiquitin B (UBB) are not on top of the list; especially as UBB is involved in several neurodegenerative diseases." (PMID 28282387, 2017).
infection (4 papers, 2011 to 2022). The state of being infected such as from the introduction of a foreign agent such as serum, vaccine, antigenic substance or organism. "Genes that were down-regulated genes at 24h post infection included inflammatory and anti-pathogen genes (CSF1 and USP2) and the cell apoptosis and death genes (MICB, BUB1B, ITGB2, UBB and BIRC3)." (PMID 23527143, 2013).
infectious disease (1 paper, 2022). A disorder directly resulting from the presence and activity of a microbial, viral, or parasitic agent in humans. "Interestingly, hub genes from age groups of 0-20 years old and 71-100 years old, namely, ARPC2, UBB, FGB, and FGG, are mostly involved in infectious diseases and the immune system." (PMID 36084955, 2022).
UBB also shares sentences with these, for which no sentence is quoted: cardiovascular disease (2 papers); colorectal cancer (2); depression (2); Down syndrome (2); endometrial carcinoma (2); bipolar disorder (1); colon carcinoma (1); COVID-19 (1); Desminopathy (1); esophageal adenocarcinoma (1); gynecological tumor (1); hepatoma (1); inflammatory myopathies (1); lung adenocarcinoma (1); memory impairment (1); myeloma (1); myotilinopathy (1); pancreatic adenocarcinoma (1); Pheochromocytoma and Paraganglioma (1); Pick disease (1); psoriasis (1); renal cell carcinoma (1); synucleinopathies (1); type 2 diabetes (1).